PPP1R15A (protein phosphatase 1 regulatory subunit 15A)
Diseases named in the same sentence as PPP1R15A in open-access papers (continued):
Sharing a sentence is not in itself a finding about the gene and the disease.
melanoma (2 papers, 2020 to 2025). A malignant, usually aggressive tumor composed of atypical, neoplastic melanocytes. "We observed in four independent mouse models of melanoma (N = 6–13 mice per model) that Perk (Eif2ak3) transcription was negatively correlated with Kdelr3 transcription, whereas Gadd34 (Ppp1r15a) transcription was positively correlated." (PMID 31949145, 2020). "Consistent with our in vitro findings, genes associated with the ATF4 (e.g., ATF4, DDIT3, PPP1R15A and CHAC1), ATF6 (e.g., ATF6B, CALR, SEL1L, and EDEM1) and XBP1 (e.g., SSR3 and DELR1) pathways were significantly enriched in melanoma TILs compared with healthy blood T cells." (PMID 40335738, 2025).
thyroid cancer (2 papers, 2025). "Increased PPP1R15A expression was related to poor prognosis in patients with thyroid cancer." (PMID 39948597, 2025).
type 2 diabetes (2 papers, 2019 to 2024). "To determine if inactivation of PPP1R15A would have a net beneficial or detrimental effect in metabolic disease, we set out to model the later stages of type 2 diabetes wherein beta-cell mass falls in the face of sustained insulin resistance." (PMID 30814564, 2019).
brucellosis (1 paper, 2024). Brucellosis is a bacterial infection that spreads from animals to people via unpasteurized dairy products or by exposure to contaminated animal products or infected animals. "Interestingly, a series of commonly upregulated genes were identified in brucellosis patients, with seven genes/transcription factors (RGS1, DUSP1, FOS, PPP1R15A, TNFAIP3, HLA‐E, and ZFP36) being the most frequent (nine times among nine clusters)." (PMID 39135683, 2024).
dilated cardiomyopathy (1 paper, 2024). Cardiomyopathy which is characterized by dilation and contractile dysfunction of the left and right ventricles. "The mice lacking functional PPP1R15A exhibited a dilated cardiomyopathy histologically characterized by loss of cardiomyocytes, a prominent immune cell infiltration, fibrosis and pro-inflammatory cytokine expression." (PMID 39312445, 2024). "Mice lacking functional PPP1R15A, exhibited dilated cardiomyopathy and severe weight loss following irradiation, whilst wild-type mice were unaffected." (PMID 39312445, 2024).
disc degeneration (1 paper, 2024). "The findings indicated that HIF-2α, CAIX, PPP1R15A, VEGFA, and EGLN3 could potentially serve as new indicators of disc degeneration." (PMID 38254196, 2024). "Measuring the target index, HIF-2α, CAIX, PPP1R15A, VEGFA, and EGLN3 could potentially serve as new indicators for disc degeneration." (PMID 38254196, 2024).
endometrial cancer (1 paper, 2023). Primary or metastatic malignant neoplasm involving the endometrium (mucous membrane that lines the endometrial cavity). "However, there are just a few studies focusing on the action of PPP1R15A in endometrial cancer progression to date, which requires more studies." (PMID 37880674, 2023).
gout (1 paper, 2025). A condition characterized by painful swelling of the joints, which is caused by deposition of urate crystals. "Elevated CDH5 levels in both AGA and CGA sera point to vascular endothelial injury as an early and sustained event in gout progression, while decreased PPP1R15A implies compromised cellular stress responses." (PMID 41511324, 2025).
heart failure (1 paper, 2024). Inability of the heart to pump blood at an adequate rate to meet tissue metabolic requirements. "We identified PPP1R15A as an essential factor in protection from radiation-induced heart failure and associated cardiac cachexia." (PMID 39312445, 2024). "Mice heterozygous for Ppp1r15a did not develop heart failure over the 22 weeks post-irradiation." (PMID 39312445, 2024). "Given that the absence of functional PPP1R15A resulted in severe heart failure, we determined whether Ppp1r15a expression was induced in the hearts of irradiated WT mice." (PMID 39312445, 2024).
keratoconus (1 paper, 2024). A degenerative, structural disorder of the eye, characterized by a cone-shaped protrusion of the cornea. "The expression of CCR2, CDKN1A, HSPA5, MAPK8IP1, PPP1R15A, and VEGFA in individuals with keratoconus was significantly different from that in control subjects." (PMID 38830963, 2024).
metastatic tumors (1 paper, 2021). "CCFs for PPP1R15A or ATM are the same or higher for all metastatic tumors compared to the periocular tumor, further suggesting that this lesion is a direct extension of the primary lesion." (PMID 34400647, 2021).
multiple sclerosis (1 paper, 2020). A progressive autoimmune disorder affecting the central nervous system resulting in demyelination. "Sephin1, a GBZ derivative that lacks α2-adrenoceptor activity, has been proposed to act as a selective inhibitor of a regulatory subunit of the stress-induced protein phosphatase 1 (PPP1R15A) with promising therapeutic potential for the treatment of multiple sclerosis." (PMID 32027884, 2020).
nutritional deficiency (1 paper, 2025). "PPP1R15A is a protein that is induced by multiple stressors, including DNA damage, heat shock, nutritional deficiency, energy depletion, and endoplasmic reticulum stress." (PMID 39948597, 2025).
osteoarthritis (1 paper, 2023). A noninflammatory degenerative joint disease occurring chiefly in older persons, characterized by degeneration of the articular cartilage, hypertrophy of bone at the margins and changes in the synovial membrane. "We therefore consider these approaches, including the study of osteoarthritis development in surgical and aging models, as the next steps in our quest to understand the role of NDRG2, WSB1, JMJD6, TSPYL2, HMGB2 and PPP1R15A in osteoarthritis and their inner mechanistic links." (PMID 37033917, 2023).
TCA cycle disorders (1 paper, 2024). "We observed that knockdown of FDX1, which is known to cause TCA cycle disorders in cuproptosis, reversed the elesclomol-induced increase in PPP1R15A expression." (PMID 38365764, 2024).
yang deficiency (1 paper, 2022). Yang deficiency is a concept from traditional Chinese medicine. "The symptomatic gene targets for Yang deficiency (KAT2B, NFKB2, CREBBP, GTF2H3) or Yin deficiency (JUNB, JUND, NGLY1, TNF, RAF1, PPP1R15A) were potentially discovered." (PMID 35341155, 2022).
infection (41 papers, 2007 to 2026). The state of being infected such as from the introduction of a foreign agent such as serum, vaccine, antigenic substance or organism. "They reported the high upregulation of the host PPP1R15A gene following Georgia 2007/1 infection." (PMID 38467747, 2024). "After infection, the initial accumulation of P-eIF2α initiates the transcription of ATF4, which in turn upregulates the expression of unfolded protein response (UPR)-associated genes, including PPP1R15A and CHOP (an inducer of apoptosis)." (PMID 28860602, 2017). "The analysis of RNA-seq data from infections of A549 cells with each virus demonstrated enrichment of ISR-regulated genes, including ATF3, GADD34 (gene name PPP1R15A), and CHOP (gene name DDIT3)." (PMID 39861909, 2025). "TNFAIP3, PPP1R15A, NFKBIA, and IFIT2 had shown bimodal gene expression in various immune cells from severely infected patients compared to healthy or moderate infection cases." (PMID 33602138, 2021). "PPP1R15A (GADD34) mediates dephosphorylation of eIF2alpha in a negative feedback loop and inhibits the unfolded protein response (UPR), and its expression was significantly upregulated by 7-fold in VSV-infected macrophages compared to mock infection." (PMID 34578166, 2021). "Previous studies like the one leaded by “The COVID19 Host Genetics Initiative” support the notion that some genetic variants, most notably at the ABO and PPP1R15A loci, in addition to SLC6A20 have a direct effect on susceptibility to infection rather than COVID19 severity." (PMID 35937703, 2022).
tumor (40 papers, 2012 to 2026). "The results revealed higher subcutaneous tumor volume and weight of the OE group than those of the EV group, indicating that PPP1R15A increases the tumorigenic ability of GC cells." (PMID 39948597, 2025). "In our studies, we found an inhibitor of PPP1R15A, Sephin1, plays a protumorigenic role in mouse tumor models." (PMID 36718369, 2023). "Quantitative real‐time PCR confirmed up‐regulation of DDIT3 (CHOP), HSPA5 (BIP), and PPP1R15A (GADD34) transcripts belonging to PERK pathway in ERO1 KO MDAMB231* tumours." (PMID 35853086, 2022). "This tumor-growth inhibitory effect of 3-HAA is at least partially attributed to its induction of apoptosis of HCC cells via upregulating PPP1R15A." (PMID 33897895, 2021). "Protein phosphatase 1 regulatory subunit 15A (PPP1R15A) showed the highest correlation with FRB-driven tumor IR and drug responses." (PMID 31552190, 2019). "Other potential tumor suppressor genes downregulated by G9a were GADD34 (PPP1R15A), a growth arrest and DNA damage-induced protein and Sprouty4 (SPRY4), an inhibitor of the Ras/MAPK signaling cascade." (PMID 25115793, 2014). "Additionally, IHC images confirmed that PPP1R15A was overexpressed in the tumor tissue of the OE group." (PMID 39948597, 2025). "Furthermore, higher expression levels of ATF3, PPP1R15A, PPP2R5B, DDIT3, and BCL10 are associated with better prognosis in HER2+-BC patients, suggesting an overall tumor-suppressive role of the UPR-driven signaling cascade." (PMID 34007022, 2021). "Increased expression of endoplasmic reticulum stress-induced transcripts such as PPP1R15A (GADD34), heat shock proteins HSPA6 and DNAJB1, and the stress-related transcription factor DDIT3 were observed in BRAFMT tumours with the highest-risk of disease relapse." (PMID 29568398, 2018). "Additionally, the drug combination upregulated PINK1, IRF1, PPP1R15A, CRABP2, SCRN1, LIMA1, and TGFBI; all genes associated with tumor suppression functions in PCa." (PMID 29545934, 2018). "The reciprocal mRNA expression patterns of G9a versus DUSP5, SPRY4, PPP1R15A in datasets as well as the protein expression patterns of G9a versus Sprouty4 and GADD34 in clinical samples strengthen the correlation between G9a and these tumor suppressive genes in OCa progression." (PMID 25115793, 2014). "Here, we present a protocol for exploring the effects of PPP1R15A inhibitor, Sephin1, on antitumor immunity of B16F1 subcutaneous tumor in mice." (PMID 37756156, 2023). "The expression level of these genes differs significantly between the tumor and normal tissues, but CREB3L3 and TRIB3, and XBP1 are overexpressed, while PPP1R15A is expressed conversely." (PMID 37880674, 2023). "In a word, PPP1R15A and its related ISR play a key role in the immune system, especially antitumor immunity, and can be used as a target for tumor immunotherapy." (PMID 36718369, 2023). "From our results, we inferred that PPP1R15A and other ISR-related genes and their protein products could be important potential targets in tumor immunotherapy." (PMID 36718369, 2023). "Top underexpressed tumor suppressor candidates such as UBXN1, HNRNPA1, PPP1R15A, and LAPTM5 may also be contributing to tumor tissue formation through inhibition of apoptosis at initial stages of cancerogenesis." (PMID 36359790, 2022). "Some of the up-regulated genes act as tumor suppressors (TXNIP, EGR1, and PPP1R15A)." (PMID 28035074, 2017).
cancer (35 papers, 2007 to 2025). A tumor composed of atypical neoplastic, often pleomorphic cells that invade other tissues. "The PPP1R15A gene was highly expressed in cancer compared with normal tissues, combining the normal samples in GTEx with TCGA-STAD." (PMID 39948597, 2025). "In-Patient 1, variants in FNIP1, PPP1R15A, WDR19, and RUNX3 were present in ~100% of cancer cells across all samples." (PMID 34400647, 2021). "Thus, cancer cell death following VCP inhibition was linked to inadequate fine-tuning of protein synthesis and activity of PPP1R15A/PP1c." (PMID 26720340, 2015). "Consistent with the observations in vitro, the mRNA levels of c-Jun target genes, Cxcl1, Dusp1, Fgb, and Ppp1r15a, regulated by ALDOA were significantly decreased in the cancer tissues of AAV8-shAldoa mice compared with AAV8-GFP mice." (PMID 40708574, 2025). "The other five genes (i.e. PPP1R15A, MOSPD2, FAM84B, GARS, KIF21B) have demonstrated involvement in the progression of various cancers." (PMID 32087735, 2020). "The results indicated both increased PPP1R15A and JUN expression levels in cancer tissues." (PMID 39948597, 2025).
PPP1R15A also shares sentences with these, for which no sentence is quoted: neurodegenerative disease (8 papers); lung carcinoma (6); ZIKV infection (6); glioblastoma (3); Hypertension (3); neuroblastoma (3); neurologic diseases (3); neuropathy (3); Parkinson disease (3); systemic lupus erythematosus (3); acute myeloid leukemia (2); bacterial infection (2); Cerebral ischemia (2); colorectal cancer (2); Dengue (2); glaucoma (2); insulinoma (2); Lung Injury (2); medulloblastoma (2); myocardial infarction (2); myocarditis (2); osteosarcoma (2); retinal degeneration (2); tauopathies (2); acute kidney injury (1); acute liver failure (1); acute lymphoid leukemias (1); adenovirus infection (1); amyloidosis (1); astrocytomas (1).
A further 67 diseases each share a sentence with PPP1R15A in 1 paper.